ING1 (inhibitor of growth family member 1)
Diseases named in the same sentence as ING1 in open-access papers (continued):
Sharing a sentence is not in itself a finding about the gene and the disease.
tumor (continued). "The INhibitor of Growth (ING) family of chromatin readers was established over 20 years ago with the identification of the tumour-suppressor ING1." (PMID 29381681, 2018). "Previous studies have shown ING1, a tumor suppressor, has a negative regulatory role on the cell cycle in various types of cancers." (PMID 30302016, 2018). "Contrary to the observations made with ING1 expression in the tumor compartment, significant results were obtained in the luminal group." (PMID 26306560, 2015). "In this particular population, stromal ING1 had better predictive value than tumor size, which is a clinically used biomarker." (PMID 26306560, 2015). "This suggests that stromal ING1 levels are equal in predictive power to the established variables of tumor grade and lymph node status in the cohort tested in this study." (PMID 26306560, 2015). "This is an interesting observation and in contrast to what was observed in the case of tumor ING1 expression." (PMID 26306560, 2015). "All ING family members (ING1-5) have been reported to be altered in localization, sequence, or expression level in various cancer types and are classified as type-II tumor suppressors." (PMID 26306560, 2015). "Consistent with a role as a tumor suppressor, inhibition of ING1 expression with antisense RNA promotes focus formation in vitro and tumor formation in vivo." (PMID 26306560, 2015). "In the analysis, tumor grade [HR 2.741, p = 0.002], lymph node status [HR 3.505, p < 0.001] and stromal ING1 [HR 2.320, p = 0.002], were significantly and independently associated with disease free survival in ER+/HER2- population." (PMID 26306560, 2015). "This is the first study to measure ING1 protein levels in human tumor tissue using fluorescence IHC and AQUA® technology." (PMID 24912621, 2014). "ING1 overexpression also blocked cancer cell metastasis in vivo and eliminated tumor-induced mortality in mouse models." (PMID 24962136, 2014). "Both Target Scan and miRanda systems predicted ING1, a key tumor suppressor, to be a putative target of miR-371-5p." (PMID 25411783, 2014). "Loss of ING proteins was generally found to correlate with cancer progression and inhibiting the function of ING1 in chromatin modification by cytoplasmic localization, also positively correlated with tumor progression in head and neck cancers." (PMID 24962136, 2014). "Most studies examining ING1 localization have proposed that cytoplasmic localization compromises the tumor suppressive function of ING1 and represents a mislocalized pool of a normally nuclear protein." (PMID 24912621, 2014). "Our experiments support the feasibility of delivering adenoviral ING1 to induce synergistic tumor cell killing in combination with IR, as a potential therapeutic strategy in OSCC." (PMID 24912621, 2014). "ING1 levels were lower in tumors compared to adjacent normal breast tissue and correlated with tumor size (p=0.019) and distant recurrence (p=0.001) in ER- or Her2+ patients." (PMID 24962136, 2014). "In silico analysis of GEO datasets (#GSE30784 and #GSE6631) revealed that ING1 mRNA was expressed at a higher level in tumor samples compared to the corresponding normal tissue in two independent HNSCC and OSCC cohorts." (PMID 24912621, 2014). "ING1 and ING2 are localized in the cell nucleus and associated with chromatin modifying enzymes, linking tumor suppression directly to chromatin regulation." (PMID 21767350, 2011).
tumor (continued). "Recently, inhibitor of growth gene (ING) family consisting of five genes, ING1 to ING5, was identified as a new tumor suppressor gene family that was implicated in the downregulation of cell cycle and chromatin remodeling." (PMID 21052543, 2011). "Recent analyses of ING1- and ING2-deficient mice confirm a tumor suppressive role of ING1 and ING2 and also indicate an essential role of ING2 in meiosis." (PMID 21767350, 2011). "This strengthens the role of ING1 as tumor suppressor and suggests an important role of the PHD and chromatin in regulation of cellular senescence." (PMID 21767350, 2011). "It is known that ING1 can act as a tumour suppressor by inducing apoptosis in damaged cells." (PMID 34493070, 2021). "Overexpression-based studies and sequence similarities to the tumour-suppressor ING1 led to the hypothesis that ING3 may be a tumour suppressor." (PMID 29381681, 2018). "Consistently, knocking out ING1 provokes a high frequency of spontaneous tumor development in mice." (PMID 28703423, 2017). "Therefore, it appears that high ING1 levels in tumor and low ING1 levels in stroma predict the best outcomes for patients." (PMID 26306560, 2015). "However, the detailed molecular mechanisms by which ING1 acts as a tumour suppressor remain incompletely defined." (PMID 25411783, 2014). "Loss of ING1 did not correlate with any clinico-pathological variables in the luminal group, whereas low ING1 expression correlated with tumor size greater than 2cm (p=0.019) as well as recurrence (p=0.030) and distant recurrence (p=0.001) in the non-luminal group." (PMID 24962136, 2014). "The ING1 epigenetic regulator and tumor suppressor plays a central role in apoptosis." (PMID 24912621, 2014). "In this context, modulating miR-371-5p could restore ING1 expression sensitizing the tumor to a combined therapy of ING1 agonists and chemotherapeutic drugs routinely employed into the clinical practice." (PMID 25411783, 2014). "Moreover, changes in ING1 expression affect cell proliferation and apoptosis, reproducing in an inverse mode the effects due to miR-371-5p, as further demonstrated in tumor samples." (PMID 25411783, 2014). "ING1 (INhibitor of Growth 1) is a type II tumor suppressor that was identified using PCR mediated subtractive hybridization between normal and cancerous breast epithelial cells followed by a functional screen for tumor induction." (PMID 22916295, 2012). "Hence, the data confirm our hypothesis that the tumor suppressors and AR co-repressors ING1 and ING2 functionally mediate the transrepression of androgen-activated AR on hTERT. * p ≤ 0.05." (PMID 34439179, 2021). "The Src phosphorylation-independent mechanism is based on the capacity of Src to bind directly ING1: in this role as cofactor, Src may prompt the degradation of ING1, or, as an alternative, kinase-dead Src may recruit and/or activate other tyrosine kinases to target this tumor suppressor." (PMID 32290470, 2020). "However, cytoplasmic localization of ING1 induces apoptosis, which, theoretically, could confer improved prognosis in patients with high levels of ING1 in their tumor cell cytoplasm." (PMID 24912621, 2014). "Neither total tumor ING1 levels nor nuclear ING1 levels were associated with DSS." (PMID 24912621, 2014). "Thus, a potential mechanism for ING1-mediated G1 cell cycle arrest could involve the inhibition of miR-371-5p, further establishing links between miRNAs and the ING1 tumour suppressor." (PMID 25411783, 2014). "ING1 and ING2, key components in mSIN3a-HDAC complexes, actively repress cell proliferation and tumor growth, also modulating hormonal-epigenetic interplay via androgen receptor signaling." (PMID 38813086, 2024).
tumor (continued). "ING1 and ING2, for example, modulate cell cycle arrest and apoptosis through androgen receptor signalling, contributing to tumor suppression." (PMID 38813086, 2024). "The ING family of tumor suppressors includes ING1–5, with the first identification of ING3 guiding the discovery of ING1–2 and 4–5." (PMID 35350574, 2022). "This work, by recognizing CG7379 and ING1 as invasion suppressors, adds further insight into the multiple roles that collectively perform ING's tumour suppressive function." (PMID 34493070, 2021). "The identification of ING1 and ING2 tumor suppressors in the AR-mediated transrepression of hTERT provides some first insights into the link between tumor suppressors and the AR (graphical abstract)." (PMID 34439179, 2021). "The degree of similarity between ING1 and ING2 led to ING2‘s classification as a type-II-tumor-suppressor protein." (PMID 31752342, 2019). "The tumour suppressor roles of ING1 and ING2 have been well established whereas candidate tumour suppressor status remains for ING3, ING4, and ING5." (PMID 31905726, 2019). "Although the founding members of the INhibitor of Growth (ING) family of histone mark readers, ING1 and ING2, were defined as tumour suppressors in animal models, the role of other ING proteins in cellular proliferation and cancer progression is unclear." (PMID 29381681, 2018). "NTZ significantly inhibited tumor growth, which resulted in decreased tumor weight and volume in the NTZ group In addition, elevated levels of ING1, LC3 and SQSTM1 were observed in the NTZ group compared with the control group." (PMID 30302016, 2018). "We find that high levels of ING1 in stroma are associated with tumor grade (p = 0.001) and size (p = 0.02), and inversely associated with patient survival (p = 0.0001) in luminal, but not in non-luminal cancers, suggesting that high stromal ING1 promotes cancer development." (PMID 26306560, 2015). "Established biomarkers such as tumor grade, tumor size, lymph node status, ER levels and HER2 status were included in the multivariate model along with stromal ING1 levels, since these variables are routinely used clinically." (PMID 26306560, 2015). "The INhibitor of Growth 1 (ING1) is stoichiometric member of histone deacetylase (HDAC) complexes and functions as an epigenetic regulator and a type II tumor suppressor." (PMID 23585863, 2013). "Taken together, these studies provide evidences that endogenous ING1 and ING2 seem to have diverse functions in tumor suppression and spermatogenesis." (PMID 21767350, 2011). "Here we summarize the activity of ING1 and ING2 as tumor suppressors, chromatin factors and in development." (PMID 21767350, 2011). "The role of ING1 and ING2 as tumor suppressor proteins is supported since both factors are involved in cellular senescence, an effective anti-tumor pathway." (PMID 21767350, 2011). "Based on these data, we further hypothesized that the ING1 and ING2 tumor suppressors are involved in the AR-mediated transrepression of hTERT." (PMID 34439179, 2021). "Animal models clearly define ING1 and ING2 as bona fide tumour suppressors." (PMID 33925563, 2021). "Mice lacking ING1 or ING2 develop spontaneous tumours including lymphomas and soft tissue sarcomas, respectively." (PMID 31905726, 2019).
cancer (30 papers, 2006 to 2023). A tumor composed of atypical neoplastic, often pleomorphic cells that invade other tissues. "Molecular analysis indicated a shared somatic driver mutation in ING1 in the eutopic endometrium and the bilateral ovaries while simultaneously exhibiting specific genetic alterations unique to each carcinoma." (PMID 38090506, 2023). "A gene-targeting experiment in mouse embryonic stem cells has shown that Ing1-null mice are viable, but are susceptible to the effect of whole-body irradiation, with a proportion of them developing spontaneous cancer as they age." (PMID 35804879, 2022). "The down-regulation of the expression of ING1 or loss of heterozygosity in the corresponding locus has been detected in several types of cancers." (PMID 35804879, 2022). "We further show that the loss of ING1 in human cancer cells also promotes invasion and disrupts cell–cell adhesion, through altered gene expression." (PMID 34493070, 2021). "Loss of chromosomal locus, translocation to the mitochondria, mutation (rarely), but mainly decreased expression of ING1 have been documented in various mammalian cancers." (PMID 34493070, 2021). "Loss of ING1 expression has been implicated in a broad range of human cancer types, including primary breast tumors, lymphoid malignancies, testis tumors, squamous cell cancers, and head and neck cancers." (PMID 26306560, 2015). "Mutations, deletions and chromosomal translocation in the genes encoding PHD finger proteins, such as the tumor suppressor ING1, have been associated with various types of cancer." (PMID 23833654, 2013). "Except for KLF4, overexpression of DEC1, p21 and ING1, which could induce cell senescence, are associated with a better survival in certain cancers, indicating that senescence may also have a protective function in cancer development." (PMID 27531889, 2016). "The Ing1 gene is functionally inactivated in many cancer types but is rarely mutated." (PMID 24912621, 2014). "As in other cancers, somatic mutations of the Ing1 gene are rare in HNSCC." (PMID 24912621, 2014). "ING family including 5 members (ING1-5) have been known as candidate TSGs with growth-inhibitory effects in addition to other restrictive influences on malignant phenotype of cancer cells." (PMID 36056353, 2022). "Recent work suggests a possible role for ING1 in cancer cell invasion and metastasis, but the molecular mechanism underlying this observation is lacking." (PMID 34493070, 2021). "Several studies investigating the effect of ING1 on cell proliferation, reported cells accumulating in G0/G1 upon ING1b overexpression in a range of cell lines from normal fibroblasts to cancer cells derived from metastatic sites." (PMID 34493070, 2021). "We identified cancer-relevant genes (ING1, ARL4C) whose expression between patients is influenced by enhancer differences in genomic copy number and germline SNPs, and HNF4α as a master trans-acting factor associated with GC enhancer heterogeneity." (PMID 34635154, 2021). "Altering ING1 levels by ectopic expression of ING1b in cancer cells promotes apoptosis, whereas altering levels by knockout in normal murine fibroblasts alters sensitivity to doxorubicin-induced apoptosis." (PMID 27551477, 2015). "ING1a was chosen, since it is believed that senescing stromal cells contribute to the induction of cancers in vivo and we here found that of the ING1 isoforms, ING1a is most effective in inducing cellular senescence." (PMID 26306560, 2015). "Previous studies have established that levels of the Inhibitor of Growth 1(ING1) tumor suppressor are reduced in a significant proportion of different cancer types." (PMID 26306560, 2015). "p33ING1b is the major ING1 isoform expressed in normal and cancer cells (any further mention of ING1 in the text refers to p33ING1b)." (PMID 24912621, 2014).
cancer (continued). "Recent studies showed that ING1 gene expression has been found to be lost in a variety of human malignancies, either alone or in combination with protein expression, showing that it is downregulated in cancer tissues compared to healthy tissues." (PMID 36056353, 2022). "For all cancers in which they are negatively regulated, ING1 and ING2 protein levels decreased in the nucleus, suggesting a mutation closer to their NLS domain and/or an impaired interaction with a protein required to target ING1 and ING2 to the nucleus." (PMID 31878273, 2019). "From our study, it appears that at least one ING-derived peptide is able to affect cancer cell viability as well as the full-length ING1 protein, and in some cases it is actually more effective in killing cells than full-length ING1 via pathways that resemble apoptosis." (PMID 27551477, 2015). "While downregulation of ING1 might promote oncogenesis in certain cancers, overexpression of ING1 might also lead to malignancy by disrupting the function of HDAC complexes." (PMID 24912621, 2014). "To examine how ING1 might limit cancer cell growth and survival, we identified genes that were regulated by ING1 using a Nimblegen microarray-based platform." (PMID 24962136, 2014). "It is worth noting that the two most susceptible lines also expressed relatively higher levels of ING1 compared to other cancer lines, but how this might be related to sensitivity is currently unknown." (PMID 22916295, 2012). "Interestingly, ING1 protein levels increase in replicative senescent cells, latter representing an efficient pathway to inhibit cancer proliferation." (PMID 21767350, 2011). "However, decreased ING1 expression and cytoplasmic mislocalization, possibly mediated by 14-3-3 proteins and the tyrosine kinase Src, have been proposed as mechanisms for the inactivation of ING1 nuclear function in many cancer-types." (PMID 24912621, 2014). "ING1 over-expression inhibited NSCLC cell proliferation, migration, and invasion, and made cancer cells undergo apoptosis, according to this research study." (PMID 31390718, 2019). "Investigation of ING1 levels in three independent cohorts using two completely independent platforms (Affymetrix gene array and AQUA®) gave consistent results in these cancers." (PMID 24912621, 2014). "In contrast, it has been shown that ING1 and ING2 play an oncogenic role in some cancers, this situation being similar to TGF-β." (PMID 21052543, 2011). "Same to ING1, ING2 affects cancer development via epigenetic mechanisms." (PMID 36056353, 2022). "In addition to the role of ING1 in regulating cell fate in non-cancerous cells, ING1 regulates a set of different pathways in cancer cells, including the induction of cellular senescence, which inhibits the cell cycle." (PMID 35804879, 2022). "Negative control of the cell cycle after overexpression of ING1 or ING2 in U2OS or normal skin fibroblast cells is consistent with the observations of overexpression of ING3 in cancer cells given their opposite involvements in HDAC and HAT complexes, respectively." (PMID 31905726, 2019). "Furthermore, experiments using the bING1-239 peptide showed that s-ING1-Ab levels were significantly elevated in sera from patients with CRC, whereas these levels were not significantly higher in sera from patients with other cancers (EC, GC, BrC, and PC) than in those from HDs." (PMID 37072777, 2023).
infection (4 papers, 2014 to 2018). The state of being infected such as from the introduction of a foreign agent such as serum, vaccine, antigenic substance or organism. "Consistent with this, and with ING1 inhibiting migratory behavior, initial scratch tests suggested that expression of ING1 by infection with adenovirus inhibited the ability of MDA-MB231 cells to migrate to fill in wounds in cell monolayers." (PMID 24962136, 2014). "Infection using Adenoviral-ING1 (Ad-ING1) reduced the viability of CAL-27, UMSCC1 and UMSCC14B cell lines." (PMID 24912621, 2014). "In addition, among 46 TRP32 target genes previously found to be differentially expressed during infection, 8 are also TRP47 targets, including CAP1, CMC1, HLX, ING1, MTFR2, NAT10, PARP16, and POLDIP3." (PMID 30408047, 2018). "Similarly to IER2, the pro-apoptotic gene ING1 was induced by MAP kinases as well, and, like IER2, showed higher mRNA levels at all timepoints after infection compared to uninfected cells under PAA treatment." (PMID 29089033, 2017).